LIMA1 (LIM domain and actin binding 1)
Diseases named in the same sentence as LIMA1 in open-access papers (continued):
Sharing a sentence is not in itself a finding about the gene and the disease.
tumor (continued). "Both has-miR-20b and has-miR-17 are OncomiRs, acting on LIMA1 tumor suppressor gene." (PMID 32938402, 2020). "Additionally, the drug combination upregulated PINK1, IRF1, PPP1R15A, CRABP2, SCRN1, LIMA1, and TGFBI; all genes associated with tumor suppression functions in PCa." (PMID 29545934, 2018). "Notably, LIMA1’s anti-tumor activity was significantly attenuated in these cells." (PMID 41596426, 2026). "In clinical use, LIMA1 IHC staining combined with current HNSCC diagnostic routines would constitute a simple and affordable upfront HNSCC diagnostic method for planning of the individualized patient therapy and follow-up strategies based on the tumor aggressiveness." (PMID 40676267, 2025). "Through these combined actions, LRP5-activated osteocytes, via LIMA1 and MYO5B, simultaneously suppress tumor growth, limit osteolysis, and alleviate the immunosuppressive milieu within the bone metastatic niche." (PMID 41596426, 2026). "Collectively, these genetic rescue experiments demonstrated that the tumor-promoting functions of BPNT1 in TNBC are largely dependent on the STUB1-mediated ubiquitination and degradation of LIMA1." (PMID 41540000, 2026). "To elucidate how LIMA1 mediates the tumor-suppressive effects of LRP5-overexpressing osteocyte-derived CM, we generated an MLO-A5 osteocyte model with LIMA1 knockdown combined with LRP5 overexpression using plasmid and shRNA transfection." (PMID 41596426, 2026). "By elucidating the LIMA1/MYO5B signaling axis, we provide a conceptual framework for osteocyte-based therapy and identify potential molecular targets for restoring bone–tumor homeostasis." (PMID 41596426, 2026). "Collectively, these findings delineate a novel oncogenic axis wherein BPNT1 scaffolds STUB1-mediated ubiquitination and degradation of LIMA1, driving EMT-facilitated tumor progression and DTX chemoresistance." (PMID 41540000, 2026). "Very weak to weak correlations were observed between the glycovariant expression of tumor samples and normal samples, the only exception being LIMA1-AAL vs. LIMA1-SBA." (PMID 38600440, 2024). "Over the past decades, researchers have identified the epithelial protein lost in neoplasm (EPLIN, also known as LIMA1) as a key regulator of cytoskeletal dynamics, cytoskeletal organization, motility, as well as cell growth and metabolism." (PMID 38732188, 2024). "In this study, glycovariants of stemness-related biomarker candidates OCT4, MET, CIP2A and LIMA1 were screened from two HNSCC cell lines and, further, from a panel of 25 HNSCC patients using samples of tumor tissue, adjacent normal tissue, and serum samples." (PMID 38600440, 2024). "E-cad and β-cat, together with several actin-binding proteins, such as α-catenin (α-cat) and Lima1 (also known as EPLIN; epithelial protein lost in neoplasm), form the adherens junction (AJ) complex." (PMID 35105859, 2022).
tumor (continued). "Fully supportive of the gain-off results above, overexpression of LIMA1 on HNSCC#17 PDX did not alter tumor size but increased the number of metastasizing HNSCC cells in the zebrafish model." (PMID 40676267, 2025). "In this model, LIMA1 silencing did not impact tumor size, but the number of metastasizing cells decreased significantly." (PMID 40676267, 2025). "In epithelial cell-derived tumors, the absence of LIMA1 can enhance tumor proliferation, invasion, migration, and angiogenesis." (PMID 38822260, 2024). "For the OTSCC cohort, Cox regression analyses with forced entry were performed for variables significantly associated with 5-year DSS in univariate analyses (N status, tumor differentiation, lymphocyte infiltration, CALML5 protein expression, and LIMA1 protein expression)." (PMID 34069237, 2021). "In addition, recent studies support the view that LIMA1 may influence tumor progression by regulating tumor-infiltrating cells in the tumor microenvironment (TME), suggesting that LIMA1 may be a potential target for immunotherapy." (PMID 40676267, 2025). "Serum LIMA1-AAL and MET-AAL indeed have a strong correlation (τ = 0.71; 95% CI: 0.45 to 0.86, p < 0.001), but neither correlates with the respective tumor expression." (PMID 38600440, 2024). "By positioning LRP5/LIMA1/MYO5B as a functional axis linking osteocytes to tumor cells, we provide a mechanistic framework in which osteocytes are not passive bystanders but active organizers of local anti-tumor responses in bone." (PMID 41596426, 2026).
cancer (31 papers, 2008 to 2026). A tumor composed of atypical neoplastic, often pleomorphic cells that invade other tissues. "Recent studies have shown that the LIMA1 gene exhibits frequent downregulation and loss in cancers, and it can be involved in the development of malignancy through various mechanisms." (PMID 37274282, 2023). "In the context of cancer, Lima1 downregulation is implicated in the progression of oral, prostate and breast cancer." (PMID 35105859, 2022). "Due to its importance in regulating actin cytoskeletal dynamics and its potential involvement in cadherin-mediated cell adhesion, the loss of LIMA1 in cancer cells may affect cellular behavior, enhancing their invasive characteristics." (PMID 39830509, 2024). "With the deepening of the LIMA1 gene research, LIMA1 has been recognized as being actively involved in cancer cell signaling, possibly through multiple protein interactions associated with cancer progression, in addition to its function as a structural protein." (PMID 37274282, 2023). "Due to the importance of LIMA1 in regulating actin cytoskeleton dynamics and its potential involvement in cadherin-mediated cell adhesion, the loss of LIMA1 from cancer cells may affect cell behavior and further enhance invasive characteristics." (PMID 37274282, 2023). "Thus, treating malignancies associated with Lima1 deficiency may benefit from cancer therapeutics that target regulators of membrane blebbing." (PMID 35105859, 2022). "LIMA1 is frequently downregulated and suppresses tumorigenesis in many cancers by activating several signaling axes, such as Wnt/β-catenin, PI3K/AKT, and FAK/Src." (PMID 41540000, 2026). "The application of LIMA1 detection in routine nmHNSCC diagnostics brings a long-needed method to the diagnostics of HNSCC primary cancers." (PMID 40676267, 2025). "After 2-year follow-up, the surgically removed HNSCC primary cancer samples were IHC stained with LIMA1 antibodies sc-136399 and RB581." (PMID 40676267, 2025). "Most of these studies suggest that LIMA1 deficiency appears to contribute to the development of EMT and metastasis of cancer cells." (PMID 37274282, 2023). "Increasing research evidences imply that LIMA1 affects cancer progression by regulating important biological processes such as actin dynamics, cell adhesion and metastasis, angiogenesis and lipid metabolism." (PMID 37274282, 2023). "Existing studies suggest that LIMA1 plays an inhibitory role in most malignant tumors, but some studies has been reported that LIMA1 exerts an oncogenic effect in the head and neck tumors." (PMID 37274282, 2023). "Recent studies, including those from our laboratory, demonstrate a broader role for LIMA1 in controlling cancer cell behaviors." (PMID 37274282, 2023). "The results showed that the mRNA level of LIMA1 was markedly downregulated in cancer tissues compared to matched adjacent para-tumoral tissues." (PMID 36497115, 2022). "Using RNA-seq data from the TCGA database, this study analyzed any differences in LIMA1 mRNA expression between normal and malignant tissues in pan-cancer." (PMID 37181789, 2022). "The markers CALML5, CD59, and LIMA1 were chosen based on their promising prognostic value presented in the Pathology Atlas and their perceived cancer cell specificity, as well as the availability of validated antibodies." (PMID 34069237, 2021). "Many of these genes, such as AKT1, RUNX1 and LIMA1, are known to be involved in cancer and related processes." (PMID 25884336, 2015).
cancer (continued). "Nevertheless, mechanisms leading to reduced LIMA1 in human cancers are incompletely defined." (PMID 41540000, 2026). "Our own findings strongly suggest that future studies should focus on isoform-selective LIMA1 detection and targeting that could provide significant help in future cancer diagnostics and anti-metastasis therapies across different cancer types." (PMID 40676267, 2025). "Therefore, this cohort provided a perfect prospective study material to challenge performance of LIMA1 IHC assay to identify patients that had an aggressive cancer besides traditionally favorable prognostic features." (PMID 40676267, 2025). "Given that LIMA1 is frequently lost in multiple cancers, deletion of LIMA1 affects the recruitment of key cytoplasmic splitting proteins at the oval groove, which leads to the formation of multinucleated cells and increases genomic instability and oncogenicity." (PMID 37274282, 2023). "Clinical pathological features and prognostic significance of LIMA1 in cancers." (PMID 37274282, 2023). "Therefore, this review systematically describes the structure and biological functions of LIMA1 and explores its expression and regulatory mechanism in malignant tumors, and further discusses its clinical value and therapeutic prospects." (PMID 37274282, 2023). "The effects of LIMA1 also extend from cell migration and cytoskeleton dynamics to cell cycle, gene regulation, angiogenesis, and lipid metabolism, among others, providing new ideas for future exploration of cancer treatment strategies." (PMID 37274282, 2023). "Next, the LIMA1 expression level in cancer tissues divided by the LIMA1 expression level in matched adjacent para-tumoral tissues was higher than 1 in the high expression group (number = 30) and less than or equal to 1 in the low expression group (number = 62)." (PMID 36497115, 2022). "In addition, LIMA1 was targeted by CAF-derived exosomes carrying miR-20a-5p, causing LIMA1 silencing and cancer suppression in HCC." (PMID 36497115, 2022). "Changes in LIMA1 expression can therefore affect carcinogenesis and cancer progression." (PMID 37181789, 2022). "Knockdown of LIMA1 has been demonstrated to enhance cancer cell invasion." (PMID 34093822, 2021). "However, relevant studies have provided conclusive evidence that reduction of LIMA1 has the potential to regulate cancer cell migration and invasion by disrupting cell-cell adhesion of adherens junctions, reducing E-cadherin expression and enhancing the EMT-like phenotype." (PMID 37274282, 2023). "In addition, loss of expression of a LUZP1-interacting tumor suppressor protein named EPLIN (also known as LIM Domain And Actin Binding 1, LIMA1) has been associated with cancer by affecting cancer cell adhesion and migration, and increasing metastatic potential." (PMID 33869174, 2021). "These could illustrate the heterogeneity of LIMA1 expression and the diversity of its functions, and more detailed studies of specific regulatory mechanisms are needed in the future to provide new insights for the development of new biomarkers and personalized cancer therapy." (PMID 37274282, 2023). "LIMA1 contributes to epithelial-mesenchymal transition (EMT) and alters cell-cell adhesion complexes, which are necessary for cancer cell migration and invasion, increase metastatic potential, and are required for cell division." (PMID 37181789, 2022). "LIM domain and actin binding 1 (LIMA1/EPLIN) is a cytoskeletal scaffold governing actin dynamics, motility, and adhesion, and functions as an EMT/metastasis suppressor often downregulated in cancer." (PMID 41540000, 2026). "Patients with high LIMA1 based on sc-136399 IHC had only 22% 5-year disease-specific survival, whereas patients with low LIMA1 had a survival of 41% in this independent cohort of HNSCC patients treated with primary cancer surgery." (PMID 40676267, 2025). "Furthermore, the prediction of surgical response by LIMA1 expression does not seem to be limited to HNSCC cancers." (PMID 40676267, 2025).
cancer (continued). "However, the expression of LIMA1 in malignant tumors and its mechanism of action have not yet been elucidated, and many problems and challenges remain to be addressed." (PMID 37274282, 2023).
Cardiovascular disease (1 paper, 2024). "Cardiovascular disease was the only comorbidity associated with two lectin assays, namely LIMA1-MAA and MET-AAL." (PMID 38600440, 2024).
LIMA1 also shares sentences with these, for which no sentence is quoted: colon cancer (4 papers); adenocarcinoma (2); esophageal cancer (2); oesophageal cancer (2); bladder cancer (1); Blindness (1); breast tumours (1); Cirrhosis (1); colon adenocarcinoma (1); cystic kidneys (1); digestive system tumors (1); gastric tumour (1); head and neck tumors (1); Hypercholesterolemia (1); Hypertension (1); laryngeal squamous cell carcinoma (1); liver disease (1); lymph node metastasis (1); medulloblastoma (1); mucinous adenocarcinoma (1); neuroblastoma (1); osteoporosis (1); prion disease (1); prostate (1); rectal cancer (1); refractory cancer of the (1); signet ring cell carcinoma (1); triple-negative breast carcinoma (1); virus infection (1).